BGN (biglycan)
Diseases named in the same sentence as BGN in open-access papers (continued):
Sharing a sentence is not in itself a finding about the gene and the disease.
pancreatic cancer (17 papers, 2010 to 2025). "Herein, we found that BGN was uniformly up‐regulated in CAFs from different cancers, including breast, colon, lung and pancreatic cancers." (PMID 36772945, 2023). "In contrast, BGN was shown to induce cell cycle arrest in pancreatic cancer cells by up-regulation of the cyclin-dependent kinase inhibitor p27." (PMID 24223213, 2013). "On the other hand, overexpression of BGN was observed in human pancreatic cancer and found to inhibit growth of pancreatic cancer cells in vitro." (PMID 24223213, 2013). "Similarly, BGN overexpression in pancreatic cancer cells inhibited the growth of cancer cells by stimulating cell cycle arrest indicating a growth suppressive function." (PMID 35053617, 2022). "In sum, this study has identified SMAD3 and BGN as novel RAC1B target genes in pancreatic cancer cells with SMAD3, in an activation-independent manner, inducing BGN, which subsequently executes inhibition of cell motility in TGF-β-dependent and/or independent fashion." (PMID 31817656, 2019). "Similarly, another SLRP protein, biglycan, was found to inhibit pancreatic cancer cell proliferation, but to favor vascular smooth muscle cell proliferation and migration." (PMID 30550571, 2018). "Overexpression of biglycan has been identified in pancreatic cancers." (PMID 20332776, 2010). "Data from mouse models of pancreatic cancer have revealed that transcriptionally active p73 (TAp73) impacts the TGF-β pathway through activation of Smad4 and secretion of biglycan (Bgn)." (PMID 38255305, 2024). "Moreover, the proteoglycan biglycan (BGN) and the glycoprotein basigin (EMMPRIN) were found to be enriched in pancreatic tumor tissue-derived EVs." (PMID 36770959, 2023).
endometrial cancer (12 papers, 2020 to 2024). Primary or metastatic malignant neoplasm involving the endometrium (mucous membrane that lines the endometrial cavity). "BGN levels in serum are reportedly associated with clinicopathological factors in endometrial cancer." (PMID 33709550, 2021). "Previous studies in colon, bladder, and endometrial cancers also provided evidences that biglycan promotes cancer cell migration, invasion, and proliferation, which ultimately result in increased resistance to 5-fluorouracil chemotherapy." (PMID 33809543, 2021). "BGN (biglycan) is a member of the leucine-rich small proteoglycan family; it can enhance the invasion, migration, and formation of endometrial cancer cells, and it can promote the invasion of GC cells by activating the FAK signaling pathway." (PMID 32908877, 2020). "The mRNA expression levels of APOE, BST1, and C1QB in endometrial cancer cell lines were significantly higher than those in normal endometrial epithelial cells, whereas BGN expression was higher in normal endometrial cell lines than in endometrial cancer cell lines." (PMID 39650066, 2024). "Among them, APOE, BGN, BST1, and BGN showed expression differences in endometrial cancer." (PMID 39650066, 2024). "In addition, BGN reportedly enhances the migration and invasion of endometrial cancer cells and is proposed as a promising EMT biomarker for colorectal cancer." (PMID 39578715, 2024). "Moreover,BGN has been reported to be an oncogene in a variety of cancers, including pancreatic, esophageal, gastric and endometrial cancer." (PMID 39578715, 2024). "We confirmed by qRT-PCR that the mRNA expression levels of APOE, BGN, BST1, and C1QB in endometrial cancer cell lines (HEC-1B and Ishikawa) were consistent with our previous results." (PMID 39650066, 2024). "In our qRT - PCR verification, the expressions of APOE, BGN, BST1, and C1QB in endometrial cancer cell lines were different from those in normal endometrial epithelial cells, which was consistent with our analysis." (PMID 39650066, 2024). "The results showed that four hub genes, APOE, BGN, BST2, and C1QB, were abnormally differentially expressed in normal tissues and endometrial cancer." (PMID 39650066, 2024). "Survival analysis indicated that only APOE and BGN were related to the overall survival (OS) and disease-free survival (DFS) of endometrial cancer patients, suggesting that they can be used as biomarkers for predicting patient survival." (PMID 39650066, 2024). "Serum biglycan levels have been studied in relation to other diseases, such as hepatitis B and endometrial cancer, but not in relation to preterm labor." (PMID 32804350, 2021). "The four hub genes (APOE, BST1, BGN, C1QB) with differential expression in endometrial cancer tissues may serve as potential therapeutic targets, warranting further research to validate their effectiveness as potential prognostic markers and treatment targets for endometrial cancer." (PMID 39650066, 2024).
osteosarcoma (12 papers, 2013 to 2025). A usually aggressive malignant bone-forming mesenchymal neoplasm, predominantly affecting adolescents and young adults. "The abnormal expressions of BGN in ovarian cancer and osteosarcoma were closely associated with chemoresistance." (PMID 31612481, 2020). "The effects of biglycan have likewise been implicated in the pathogenesis of osteosarcoma, primary malignant tumor of the bone." (PMID 30406034, 2018). "TNC, LUM, COL12A1, COL6A3, and BGN are among the DEPs that differentiate the chondroblastic group from other subtypes of osteosarcoma." (PMID 37681913, 2023). "Herewith, we propose a potential direct and adjunct therapeutical implication of the ECM effector biglycan in osteosarcoma." (PMID 35267503, 2022). "This signaling results in increased MG63 osteosarcoma cells’ aggressiveness and chemoresistance to doxorubicin, suggesting a potential direct and adjunct therapeutical implication of biglycan in osteosarcoma." (PMID 35267503, 2022). "In conclusion, these data indicate a potential direct and adjunct therapeutical role of biglycan in osteosarcoma." (PMID 35267503, 2022). "Conversely, in MG63 osteosarcoma cells or the osteoblastic cell line, biglycan mRNA expression increased with IGF-1 treatment." (PMID 33573338, 2021). "Specifically, biglycan favors MG63 osteosarcoma cell proliferation via a LPR6/β-catenin/IGF-1R signaling axis and functions in a positive feedback loop regulating osteosarcoma growth." (PMID 34917515, 2021). "Key downstream mediators of biglycan have been correlated to osteosarcoma development and prognosis." (PMID 30406034, 2018). "Our findings revealed that biglycan through an LPR6/β-catenin/IGF-IR signaling axis positively regulates MG63 osteosarcoma cell growth." (PMID 30406034, 2018). "Specifically, biglycan has been identified as a product involved in resistance to chemotherapy-resistant pediatric osteosarcoma." (PMID 30406034, 2018). "In order to identify possible partners/mediators of biglycan action we screened the effect of key regulators of osteosarcoma growth on biglycan expression." (PMID 30406034, 2018). "Since in the present study, we showed an enhancement of biglycan expression through IGF-IR downstream effects we examined the possible involvement of IGF-IR in biglycan-dependent osteosarcoma cell growth." (PMID 30406034, 2018). "In the present study biglycan was identified as a positive regulator of MG63 osteosarcoma cell growth (p ≤ 0.001)." (PMID 30406034, 2018). "We examined the possibility of a cross-talk between IGF-IR and Wnt/β-catenin pathways in the biglycan effect on osteosarcoma growth." (PMID 30406034, 2018). "In summary, we report a novel mechanism where biglycan through a LRP6/β-catenin/IGF-IR signaling axis enhances osteosarcoma cell growth." (PMID 30406034, 2018). "In order to investigate the effect of biglycan on the Wnt pathway in osteosarcoma cells, β-catenin expression was studied after incubation of the cells with biglycan for 48 h." (PMID 30406034, 2018). "For instance, decorin was shown to slow the migration rate of osteosarcoma cells by a mechanism depending on its CS/DS chain, while CS/DS-PGs biglycan and decorin, independently of their CS/DS, increased mobility of lung fibroblasts." (PMID 23843960, 2013). "Furthermore, biglycan was shown to upregulate MG63 osteosarcoma cells ERK 1/2 activation, previously correlated to their chemoresistance profile." (PMID 35267503, 2022). "Indeed, biglycan interacts with the IGF-IR signaling pathway to enhance the proliferation of osteosarcoma cells." (PMID 35267503, 2022). "Previously, we reported that IGF-I increases biglycan expression in MG63 osteosarcoma cells." (PMID 35267503, 2022). "Interestingly, the cAMP/protein kinase A signal transduction pathway was found to enhance biglycan expression in osteosarcoma cells." (PMID 35267503, 2022). "Notably, biglycan treatment in our osteosarcoma model attenuated PTEN mRNA expression levels (p ≤ 0.05)." (PMID 35267503, 2022).
osteosarcoma (continued). "Biglycan has been shown to induce IGF-IR/ERK 1/2 signaling in osteosarcoma cells." (PMID 35267503, 2022). "The MG63 cells are a poorly differentiated, aggressive osteosarcoma model expressing biglycan." (PMID 35267503, 2022). "In addition, biglycan was shown to control osteosarcoma cell proliferation through a LRP6/β-catenin/IGF-IR signaling axis." (PMID 35267503, 2022). "Notably, biglycan is one of nine outstandingly differentially expressed osteosarcoma genes between responders and poor responders to chemotherapy." (PMID 35267503, 2022). "Some reports relate biglycan function with the pathogenesis of osteosarcoma." (PMID 35267503, 2022). "We have previously shown that biglycan is a potent modulator of osteosarcoma cells' migration." (PMID 30406034, 2018). "Defining and targeting the components of the biglycan signaling loop on an individual patient may basis offer ground for the generation of tailor-made osteosarcoma strategies?" (PMID 30406034, 2018). "Likewise, we demonstrate for the first time that treatment of MG63 osteosarcoma cells with recombinant biglycan increases β-catenin expression and mediates its cellular deposition and enhancingβ-catenins' cell membrane and cytoplasmic localizations." (PMID 30406034, 2018). "In the present work, taking into account the importance of biglycan and its downstream mediators in the functional regulation of osteoblastic lineage cells, we examined the effect of biglycan on osteosarcoma cell growth as well as the putative mechanisms involved." (PMID 30406034, 2018). "Transcription of the BGN, biglycan, promoter in bone cells was found to be increased due to elevated levels of intracellular cAMP, which in turn implicates cAMP/protein kinase-A signal transduction pathway in the regulation of biglycan gene expression in osteosarcoma." (PMID 37681913, 2023). "Therefore, we aimed to assess whether osteosarcoma cells of different differentiation and biglycan expression status utilize the mentioned mechanism." (PMID 35267503, 2022). "Therefore, biglycan exhibits doxorubicin protective effects in MG63 osteosarcoma cells." (PMID 35267503, 2022). "We have previously shown that biglycan positively modulates poorly differentiated and biglycan-expressing MG63 osteosarcoma cell growth through an IGF-IR/β-catenin/ERK1/2 signaling conduit." (PMID 35267503, 2022). "In summary, we report for the first time that biglycan, a class I SLRP, can bind to IGF-IR and enhance the growth and aggressivity markers of MG63 osteosarcoma cells." (PMID 35267503, 2022). "More recently, a link between biglycan and Wnt/LRP6 signaling was additionally reported in the context of osteosarcoma." (PMID 34917515, 2021). "We recently showed that biglycan enhances both basal and IGF-1-dependent osteosarcoma cell proliferation." (PMID 34069554, 2021). "Therefore, we examined whether in our osteosarcoma model biglycan interacts with the LRP6 receptor." (PMID 30406034, 2018). "Furthermore, osteosarcoma markers of poor response to therapy (Huvos grade I/II response defines tumors with little or no response to chemotherapy) are predominantly gene products involved in microenvironmental remodeling and osteoclast differentiation, including biglycan." (PMID 30406034, 2018). "In summary we report a novel mechanism where biglycan, an ECM proteoglycan, through a LRP6/β-catenin/IGF-IR axis enhances osteosarcoma cell growth." (PMID 30406034, 2018). "IGF-IR activation results in increased biglycan secretion thus, forming an autonomous ECM-originating signaling loop which contributes to osteosarcoma growth." (PMID 30406034, 2018). "Furthermore, the TGF-beta/ALK5 effect on p38 activation and BGN expression was also impacted by overexpression of GADD45beta alone in PANC-1 and osteosarcoma MG-63 cells." (PMID 41373732, 2025).
osteosarcoma (continued). "The role of biglycan in osteosarcoma is not well established even though the expression of this SLRP changes in osteosarcoma, partly correlated to the cancer differentiation status." (PMID 35267503, 2022). "To better understand this mechanism, we tested if biglycan affects the proliferation of the biglycan non-expressing U-2OS and Saos-2 osteosarcoma cells." (PMID 35267503, 2022). "As IGF/IGF-IR also enhances biglycan expression in MG63 cells, this mechanism could plausibly be a vicious loop supporting osteosarcoma cell growth and contributing to the initiation of IGF-correlated chemotherapy resistance." (PMID 34069554, 2021). "Moreover, in the osteosarcoma model, we have identified an IGF-IR/biglycan loop, which regulates these cells’ growth, suggesting possible critical interaction between the ECM and IGF-IR in the modulation of both tumor growth and angiogenesis." (PMID 34069554, 2021). "Biglycan, thus, through a wnt/β-catenin/IGF-IR signaling axis, enhances osteosarcoma cell growth." (PMID 34069554, 2021). "Therefore, biglycan regulates the protein expression and localization of β-catenin in MG63 osteosarcoma cells." (PMID 30406034, 2018). "Due to the fact that, IGF-I/IGF-IR is a key signaling pathway of bone anabolic processes and established in early reports to regulate osteosarcoma cell proliferation we wanted to verify its putative action on MG63 cell growth and assess possible connection to biglycan effects." (PMID 30406034, 2018). "Biglycan can stimulate the growth of mesenchymal-derived tumor cells: such mechanisms have been investigated, and biglycan was found to modulate the insulin-like growth factor receptor I (IGF-IR) and Wnt/β-catenin signaling cascade, thereby promoting osteosarcoma cell proliferation." (PMID 39334952, 2024). "Therefore, biglycan was shown to modulate significantly both basal and IGF-I induced cell proliferation of MG63 cells, suggesting an interplay between biglycan and IGF-I signaling in the regulation of osteosarcoma growth." (PMID 30406034, 2018).
diabetes (10 papers, 2012 to 2025). "The biglycan overexpression, which is thought to be associated with hyperinsulinemia, might also be considered as evidence of diabetes-related metabolic disorders." (PMID 32821344, 2020). "And it is emphasized the significance of biglycan as a hopeful therapeutic target in malignant tumors with diabetes." (PMID 32821344, 2020). "It is considered that biglycan expression is promoted by AKT activation even in diabetes showing hyperinsulinemia, which activates AKT." (PMID 32821344, 2020). "In conclusion, our study suggests that diabetes promotes liver metastasis of CRC via biglycan, which induces cancer stemness and EMT from interaction with MSCs." (PMID 32821344, 2020). "Biglycan expression is also increased in adipocytes in diabetes and is related to insulin resistance and fat inflammation." (PMID 32821344, 2020). "In renal glomeruli, biglycan expression increases in diabetes and correlates with the development of diabetic nephropathy." (PMID 32821344, 2020). "There are many reports on the overexpression of biglycan and the promotion of diabetic complications in diabetes patients." (PMID 32821344, 2020). "At the molecular level, diabetes can lead to the upregulation of biglycan, which may contribute to aortic valve degeneration." (PMID 35284496, 2021). "Biglycan holds great potential as biomarker as deregulated levels of soluble biglycan are detected in a variety of inflammatory and chronic disease, such lupus nephritis, diabetes, fibrosis, renal diseases, and cancer, biglycan holds great potential as biomarker." (PMID 34917515, 2021). "The results showed that biglycan, but not decorin or lumican was upregulated in degenerated human aortic valve cusps, hypothesizing that biglycan represents a potential link between degenerative aortic valve disease and diabetes." (PMID 34561944, 2021). "In diabetes, biglycan expression in aortic stromal cells is increased and promotes its destruction." (PMID 32821344, 2020). "Regardless of the presence of diabetes, obese patients had significantly higher biglycan mRNA in both visceral and subcutaneous adipose tissue." (PMID 27465988, 2016). "We noted that adipose tissue biglycan mRNA was elevated in obese patients regardless of the presence of diabetes." (PMID 27465988, 2016). "A Japanese study suggested that diabetes mellitus may be associated with liver metastasis of colorectal cancer through the production of a biglycan-rich cancer stroma, negatively affecting the prognosis, representing another intriguing theory about the relationship between CRC and diabetes." (PMID 38835644, 2024). "In contrast to Psammomys obesus, in which biglycan mRNA expression is higher in VAT than in SAT16, its expression was similar in the two fat depots in our study subjects (regardless of obesity or diabetes); this disparity is likely due to species differences." (PMID 27465988, 2016). "Thus, DM-CRC has higher malignant phenotypes compared to non-DM-CRC, and the involvement of diabetes-induced biglycan may act as a pathogenic factor." (PMID 32821344, 2020). "In addition, diabetes significantly increased the level of HSP70, whereas the levels of HSP60 and biglycan were not affected." (PMID 26398934, 2015).
myocardial infarction (9 papers, 2014 to 2025). Gross necrosis of the myocardium, as a result of interruption of the blood supply to the area, as in coronary thrombosis. "In contrast to Guidetti and colleagues, we found a role for biglycan in arterial thrombosis that is causative for myocardial infarction and stroke." (PMID 34830059, 2021). "Biglycan deficiency leads to disturbed collagen deposition, disturbed remodeling and hemodynamic insufficiency after myocardial infarction with subsequent ventricular rupture." (PMID 25875863, 2015). "The proteoglycan BGN is an extracellular matrix component critically involved in collagen fibrillogenesis and adaptive remodeling after myocardial infarction, and its upregulation is responsible for impaired fibrotic scar deposition in the heart tissue." (PMID 36675295, 2023). "After myocardial infarction, biglycan plays a major role for stable collagen matrix formation and for the preservation of cardiac left ventricle function." (PMID 34830059, 2021). "Biglycan also supports the regeneration of the heart after myocardial infarction." (PMID 30538173, 2019). "Biglycan is also required for adaptive remodeling after myocardial infarction." (PMID 24667694, 2014).